VIM (vimentin)
Diseases named in the same sentence as VIM in open-access papers (continued):
Sharing a sentence is not in itself a finding about the gene and the disease.
breast carcinoma (continued). "Therefore, RNF208 plays a negative role in aggressive breast cancer progression by destabilizing AKT-mediated phosphorylation of soluble Vimentin." (PMID 31862882, 2019). "To expose some molecular mechanisms by which Pax-5 could suppress breast cancer aggressive features, we performed RT-qPCR on molecular mediators of breast cancer malignancy such as: MMP2 and MMP9; vimentin and fibronectin following Pax-5 transfection of MB231 cells." (PMID 28076843, 2017). "In order to examine the effects of melatonin on breast cancer stem cells from canine and human cell lines, the protein expression of the cancer stem cell marker OCT4, the epithelial marker E- cadherin, the mesenchymal markers N-cadherin and vimentin, were measured in cells from mammospheres." (PMID 26934679, 2016). "Vimentin is normally expressed by MDA-MB-231 breast cancer cells, but not by MCF-7 cells." (PMID 27725631, 2016). "We have identified 48 genes that can induce VIM protein in the absence of EGF in the breast cancer cell line MDA-MB-468, suggesting they may be capable of initiating EMT." (PMID 27876705, 2016). "In this study, we found that AESN could attenuate N-cadherin, vimentin, and ZEB1 levels of MCF-7 breast cancer cells after 24 h treatment, revealing that AESN may demonstrate chemotherapy resistance, metastasis, and cancer cell migration as well as suppress cancer cell proliferation." (PMID 27136519, 2016). "Their data suggested that P-cadherin and Vimentin could be adjunctive to the commonly used IHC surrogates for basal-like breast cancer identification, but not for predicting disease outcome." (PMID 26821054, 2016). "E-cadherin and Vimentin were reported played crucial roles in epithelial-mesenchymal transition (EMT) process, including monolayer scattering, independent growth, migration, and invasion, of breast cancer cells, which closely related to metastasis of cancer cells." (PMID 26516313, 2015). "In addition, consistent with a previous study on breast cancer, ectopic expression of GATA3 could also inhibit TGF-β1-induced EMT in 22RV1, as evident by increased E-cadherin expression and decreased Vimentin and Snail expression." (PMID 26451614, 2015). "Vimentin, Zeb1 and Sip1 are high in TNBC compared to non-TNBC cells and it was also shown that over expression of vimentin is associated with poor prognosis of breast cancer." (PMID 25268751, 2014). "The weakly invasive head and neck squamous cell carcinoma (HNSCC) cell line HN-4 and human breast cancer cell line MCF-7 exhibited a characteristic epithelial cobblestone-like morphology with high expression of the epithelial marker E-cadherin and low expression of the mesenchymal marker Vimentin." (PMID 24885626, 2014). "Similarly, expression of miR-100 in the MCF7 human epithelial breast cancer cell line also markedly downregulated E-cadherin and upregulated vimentin, although we did not observe a clear morphological change." (PMID 24586203, 2014). "Vimentin proteolysis was rescued in the presence of mevalonate and may play a role in protecting from statin-induced breast cancer cell death as vimentin expression was not altered in normal mammary epithelial cells." (PMID 25268751, 2014). "Interestingly, in two patients we observed a rare solid structure, lacking squamous metaplasia but with a distinctly vimentin-positive mesenchymal immunophenotype which was similar to our findings for basal-like breast cancer cell line spheres." (PMID 23750209, 2013). "This experiment was first attempted in MCF7 and MDA MB 468 breast carcinoma cells, both of which do not have detectable vimentin by western blotting; however in these cases, cells were also not motile so the experiment could not be performed (data not shown)." (PMID 24069380, 2013).
breast carcinoma (continued). "Expression of vimentin is characteristic of epithelial cells undergoing the EMT process and is related to reduced expression of E-cadherin and upregulation of N-cadherin, while increased expression of vimentin in breast carcinomas is correlated with poor prognosis." (PMID 21663619, 2011). "A decrease in microtentacle frequency was observed in noninvasive, non-vimentin-expressing breast carcinomas or in cells expressing a dominant-negative vimentin mutant that promotes vimentin filament disruption or after cell treatment with inhibitors of PP1/PP2A phosphatases." (PMID 20169076, 2010). "We have shown in this study that breast cancer cells can exhibit partially induced EMT, where Snail induction as a result of hypoxia does not elicit a motile phenotype even though levels of mesenchymal markers such as vimentin are increased and E-cadherin levels decrease." (PMID 19844232, 2009). "Exposure of these breast cancer cell lines to severe hypoxia induced a shift towards an EMT phenotype, with elevated levels of Snail protein in all the cell lines, decreased expression of E-cadherin in MCF-7 cells and increased vimentin expression in MDA-MB-468 and MDA-MB-231 cells." (PMID 19844232, 2009). "Previous studies have shown that MCF-7 breast cancer cells do not typically express VIM but exhibit strong expression of KRT; the acquisition of VIM expression and the loss of KRT19 expression were associated with adriamycin-resistant MCF-7 cells compared with their parental cells." (PMID 19087274, 2008). "However, our data suggest that wildtype vimentin is non-tumorigenic in breast cancer, inferring that the effect of vimentin in cancer may be tissue specific, which has never been reported." (PMID 40690373, 2025). "Moreover, to examine whether vimentin is sufficient to induce nuclear dysmorphia, breast cancer MCF7 cells that do not express endogenous vimentin and exhibit normal nuclear shape were employed." (PMID 39542246, 2024). "In this study, the observed increase in Snail1, Vimentin and MMP-9 expression as well as the reduction in E-cadherin expression in the BT549-liposome-CD147 group suggests that CD147 may contribute to EMT and facilitate tumor invasiveness in certain breast cancer cases." (PMID 38066486, 2023). "In addition, the expression level of E-cadherin was up-regulated and expressions of Vimentin, MMP-2, MMP-9, Slug and Snail were reduced in the xenografts in the KIF3B-shRNA group compared with the control group by IHC staining, which were consistent with the results in breast cancer cell lines." (PMID 33542902, 2020). "The SYK inhibitor, BI 1002494, caused no increase in proliferation in breast cancer cells or primary mammary epithelial cells in 2D or 3D cultures, nor changes in proliferation (CD1/2, CDK4, PCNA, Ki67) or invadopodia markers (MMP14, PARP, phospho-vimentin Ser56)." (PMID 32292575, 2020). "Consequently, MTF might reduce the invasive capacity of mesenchymal primary breast cancer cells by lowering SNAIL and Vimentin, which are also important factors involved in the structural changes of the cytoskeleton and thus in cell motility and invasiveness creating a phenotypic switch." (PMID 31337349, 2019). "The analysis of VIMENTIN and SNAIL mRNA levels in those tumors also ruled out major alterations in EMT that contribute to metastasis in breast cancer." (PMID 40952912, 2025). "As expected from previous experiments, in this set up the epithelial ZR75-1 breast cancer cells stained positive for Pan-CK, HER2 and Ki67, whereas the T98G glioblastoma cell line was positive for Ki67 and vimentin but remained negative for Pan-CK and HER2." (PMID 40558484, 2025). "The gene most upregulated by the C328S vimentin, as found in the RNA-Seq analysis, which is a long non-coding RNA XIST, is known to induce proliferation, invasion, and inhibit apoptosis in breast cancer." (PMID 40690373, 2025).
breast carcinoma (continued). "Invasive luminal B breast cancer LCs were reported to express epithelial markers KRT14 and p63 but lacked expression of typical EMT markers TWIST1, Slug, and vimentin." (PMID 39408880, 2024). "The stable overexpression of USP29 in luminal breast cancer cell MCF‐7 decreased the level of epithelial marker E‐cadherin and increased the expression of mesenchymal marker Vimentin, whereas the 3A mutant failed to induce such phenotypes." (PMID 36782089, 2023). "Vimentin (VIM) has been demonstrated to be a mesenchymal marker that is expressed in some cancer types, including breast cancer, and its effect on migration is not significant." (PMID 37700593, 2023). "Our results indicated that silencing of NONO reversed the high expression of vimentin and low expression of E-cadherin in breast cancer cells, thereby inhibiting the metastasis and EMT of breast cancer cells." (PMID 37370134, 2023). "Inhibition of miR-29a in the mammary tumor mice significantly suppressed the lung metastasis, reduced the expression of EMT markers fibronectin, vimentin and snail, but did not affect the primary tumor growth." (PMID 37081505, 2023). "The overexpression of vimentin has also been shown to increase integrin traffic, migration, and invasion in a vimentin-negative MCF7 breast cancer cell line." (PMID 34577566, 2021). "Although ZEB1 and VIM were not distinctly upregulated, the overall EMT program was higher in resistant cells than in sensitive breast cancer cells." (PMID 34316714, 2021). "In immunofluorescence using primary isolated mammary cancer cells incubated with SMP30, pan-cytokeratin, and vimentin antibodies, primary carcinoma cells were negative for vimentin (green)." (PMID 33652881, 2021). "MDA-MB-231 is a human mesenchymal breast cancer cell line (triple-negative subtype: ER-, PR-, HER2-, claudin-low), lacking E-cadherin expression and showing 100% vimentin positivity." (PMID 32053991, 2020). "The epithelial markers (CK18 and CK19) were expressed in all breast cancer cell lines, whereas the mesenchymal markers (PLS3, vimentin, and N-cadherin) were expressed mainly in the non-epithelial cell lines." (PMID 31947504, 2020). "In our study, serum levels of vimentin and DAPK1 have been shown to be elevated in Ghanaian breast cancer patients than in their non-cancer counterparts." (PMID 28616237, 2017). "While, overexpressing of ICAM-1 were increased the expression of vimentin and ZEB in non-metastatic breast cancer cells." (PMID 29137327, 2017). "These p120 negative mammary tumors presented with anaplastic histological features and expression of basal markers such as CK14 and/or vimentin." (PMID 27411687, 2016). "In contrast, MDA-MB-231 basal breast cancer cells displayed basal markers CK14 and vimentin, but not the luminal markers CK8 and CK18." (PMID 26147507, 2015). "The objective of this study was to detect EMT phenotype through Vimentin (VIM) and Slug expression in cytokeratin (CK)-negative CTCs in non-metastatic breast cancer patients and to determine the importance of EGFR in the EMT phenomenon." (PMID 25277187, 2014). "Taken together, these results indicated that in addition to vimentin, MTHFD2 depletion reduced N-cadherin expression but did not significantly modulate ZEB1, ZEB2 and SLUG transcription in MDA-MB-231(SA) breast cancer cells." (PMID 23295955, 2013). "We selected two cell lines that do not express the human ALOX15 gene, including a vimentin-expressing mouse fibroblast cell line (NIH3T3) and a human breast cancer cell line (MCF-7), a vimentin-lacking cell lines." (PMID 22879973, 2012). "Exposure of non-aggressive breast cancer cells to conditioned media from senescent fibroblasts induces EMT hallmarks, including downregulation of β-catenin and E-cadherin and upregulation of vimentin, reflecting a mesenchymal phenotype." (PMID 41154660, 2025).
breast carcinoma (continued). "However, vimentin failed to reveal differences at either the mRNA level or in the cell-staining setting, possibly due to its non-specificity between MDA-MB-231 breast cancer cells and fibroblasts." (PMID 36831470, 2023). "In addition, there was no alteration in the migration activity, confirming that 5-Aza-CdR had no direct effect on the expression of VIM and CDH1 in breast cancer cells with a low level of SIPA1 expression." (PMID 32193333, 2020). "Further studies in MDA-MB-231 breast cancer cells reveal that TS subpopulation expresses higher levels of SLUG, SNAIL, VIMENTIN and N-CADHERIN while show a lack of expression of E-CADHERIN and CLAUDIN, being this profile characteristic of the epithelial-to-mesenchymal transition (EMT)." (PMID 26752044, 2016). "In fact, we have recently demonstrated important role of Vimentin/Slug EMT markers in tumor growth of primary breast cancer patients and in circulating tumor cells (CTCs) EGFR+ from cytokeratin negative non-metastatic breast cancer patients." (PMID 26752044, 2016). "Recently, VIM was reported to be upregulated in response to alcohol in Caco-2 (colon cancer), MCF-7 and MDA-MB-231 (breast cancer), and IEC-6 (nontransformed, normal intestinal) cell lines further suggesting the presence of alcohol etiology in the Conserved-Net." (PMID 22539975, 2012). "While proteins such as vimentin and Plastin 3 showed no notable changes, other EMT markers like Keratin 5 and E-Cadherin were affected, suggesting that although similar pathways may be involved, distinct proteins play central roles in breast cancer and NSCLC." (PMID 40301999, 2025). "Although CCL18 induces the increased vimentin and decreased E-cadherin, as well as the upregulation of GM-CSF, IL-8, CCL2, and GRO, the upregulated levels of IL-8 in breast cancer cell might be not enough to induce the enrichment of cancer stem cell and mediate chemoresistance." (PMID 36418470, 2023). "Interestingly, immunofluorescence staining showed that the reduced E-cadherin and increased vimentin, which were induced by CCL18 as previously reported, were alleviated in the MCF-7 breast cancer cells transfected with miR98 mimics, but not with irrelevant negative controls." (PMID 26244871, 2015). "To confirm that the cells characterised as CTCs in breast cancer patients were nonhematopoietic cells presenting ectopic cytokeratin expression, we performed triple-immunofluorescence experiments using antibodies against CKs and CD45 along with antibodies against Twist or vimentin." (PMID 21663619, 2011). "Besides some published potential biomarkers of breast cancer bone metastasis were identified in our study, we also detected some novel biomarkers or their relationship with breast cancer bone metastasis has never been reported, such as TNFAIP6, DHRS3, ASS1, RIPK4, VIM, CD200." (PMID 30918839, 2019). "However, expression of E-cadherin and vimentin was not changed in areas with nuclear Snail staining, suggesting that Snail can be upregulated without affecting the expression of other EMT markers in vivo, as was also demonstrated in our breast cancer cell lines." (PMID 19844232, 2009).
lung carcinoma (366 papers, 2009 to 2026). "On the other hand, several genes in lung cancer, such as Twist, Snail, and TGF-β1, have been confirmed to be associated with EMT, promoting the process of EMT in lung cancer by downregulating E-cadherin and upregulating Vimentin." (PMID 40304000, 2025). "This makes vimentin a useful diagnostic marker in differentiating between the different subtypes of lung cancer." (PMID 39796712, 2024). "Here, we show that various cell types (normal and vimentin null fibroblasts, mesenchymal stem cells, and A549 lung carcinoma cells) attach to and spread on polyacrylamide hydrogel substrates covalently linked to vimentin." (PMID 37356720, 2023). "In lung cancers, vimentin has been shown to be the target of various regulating factors that control expression or cause post-translational modification of vimentin." (PMID 35573702, 2022). "Treatment-naïve exosomes from HNSCC patients were able to induce EMT in vitro with loss of E-cadherin expression and gain of vimentin expression, as it was reported for hepatocellular carcinoma or lung cancer." (PMID 36686733, 2022). "In this study, we verify the significance of vimentin in metastasis promotion of MTAP‐deficient lung cancer." (PMID 35766227, 2022). "CD82 is a tetraspanin that, when expressed at low levels and in the context of elevated Vimentin expression, was associated with a worse lung cancer patient prognosis." (PMID 35280793, 2022). "In our study, we also observed the migration activity was impaired in MTHFD2-deficient lung cancer cells by affecting gene and protein expression of Zeb1, Vimentin and Snail." (PMID 35790743, 2022). "PI3K and MEK inhibitors downregulated the process of EMT and biological behaviors of lung cancer cells, probably through alteration of vimentin‐associated cytoskeletons." (PMID 34323425, 2021). "TGF-β1 induced EMT in lung cancer cells, resulting in loss of cell polarity, decreased expression of epithelial marker E-cadherin, and increased expression of mesenchymal marker Vimentin (Massagué, 2008)." (PMID 35111070, 2021). "Exogenously overexpressed LNC CRYBG3 increased the metastatic ability and the protein expression level of the metastasis-associated proteins Snail and Vimentin in low metastatic lung cancer HCC827 cell line." (PMID 33809929, 2021). "PI3K and MEK inhibitors downregulated the process of EMT and biological behaviors of lung cancer cells, probably through altering vimentin‐associated cytoskeletons." (PMID 34323425, 2021). "We studied the mechanisms implicated in the progression and invasion of lung cancer (apoptosis, invasion capacity and vimentin expression) due to CSE and EZH2-mediated, using A549 rather than 16HBE in “in vitro”." (PMID 31666665, 2019). "Our results showed that downregulation of TRPM7 protein expression in the lung cancer cells, was associated with concomitant downregulation of vimentin mRNA expression, while the mRNA expression of E-cadherin, p21 and BAK was upregulated." (PMID 30477473, 2018). "Herein, we showed that the presence of mutated-EGFRs in lung cancer cells enhances cell mobility and promotes vimentin protein, a hallmark of mesenchymal cells." (PMID 28881820, 2017). "Up-regulation of vimentin intermediary filaments has been implicated in epithelial-to-mesenchymal transition and increased migratory capacity in lung cancer cells in an AKT-dependent fashion." (PMID 28798482, 2017). "We identified aptamer-associated protein biomarkers for lung cancer such as vimentin, annexin A2, annexin A5, histone 2B, neutrophil defensin, and clusterin." (PMID 26061649, 2015). "The loss of vimentin has been investigated in many tumor types, including prostate cancer, gastric cancer, lung cancer, malignant melanoma, central nervous system tumors, and CRC." (PMID 25431208, 2014).